LPP (LIM domain containing preferred translocation partner in lipoma)
Diseases named in the same sentence as LPP in open-access papers (continued):
Sharing a sentence is not in itself a finding about the gene and the disease.
tumor (continued). "In LUSC, a statistically higher level of methylation can be observed for the promoter region of the LPP gene in tumor tissue, though the B-value for both tumor and normal is below 0.05, meaning that less than 5% of all samples included in analysis are methylated at this region in LUSC." (PMID 41441397, 2025). "Current studies demonstrate that both DDX27 and LPP are involved in the tumor EMT process." (PMID 35601484, 2022). "LPP promotes tumor angiogenesis and confers chemoresistance to ovarian cancer." (PMID 35601484, 2022). "Recently, LPP has emerged as a critical inducer of tumor cell migration, invasion and metastasis." (PMID 34150649, 2021). "In the context of tumor progression and spreading, LPP may in fact facilitate the abnormal migratory behavior of cancer cells by playing a regulatory role in the formation and function of invadopodia that promote metastasis." (PMID 34867475, 2021). "LPP has emerged as a critical inducer of tumor cell migration, invasion and metastasis." (PMID 34150649, 2021). "The association of LPP with metastasis and infiltration in many types of cancer suggests that it may also serve as marker to evaluate the severity of the disease, high expression levels of LPP often indicating a high degree of tumor malignancy." (PMID 33371071, 2020). "This last observation suggests that LPP silencing reduced tumor angiogenesis." (PMID 31652539, 2019). "LPP and the expression of fusion proteins probably mediate tumor growth." (PMID 28719625, 2017). "Thus, we next investigated the potential role of LPP in promoting tumour cell extravasation using an ex ovo chick chorioallantoic membrane (CAM) assay." (PMID 28436416, 2017). "In the context of cancer progression, where uncontrolled migration of and invasion by tumor cells is a pivotal feature, this effect of LPP on ETV5-dependent gene expression may reinforce epithelial-to-mesenchymal transition and expansion of the tumor into neighboring tissues." (PMID 34867475, 2021). "In cancer, enhanced tumor angiogenesis and micro‐vessel leakiness were attributed to activation of MFAP5 downstream of YAP or MFAP5‐induced expression of LPP." (PMID 41348119, 2025). "In our study, LPP suppressed metastasis-related phenotypes and EMT and served as a tumor suppressor in BCa." (PMID 37422473, 2023). "This fusion protein, in which the carboxy-terminal LIM domains of LPP are fused to the amino-terminal end of HMGA2, has been shown to facilitate the migration of tumor cells." (PMID 34867475, 2021). "Lungs were harvested 3 weeks post resection for cohorts bearing NMuMG-ErbB2 tumours, and 4 weeks post resection for mice bearing NIC tumours (LucA- and LPP-shRNAs)." (PMID 28436416, 2017). "Interestingly, both LPP/α‐actinin and their co‐localization are reduced at FAs in RITA‐depleted tumor cells and MEFs." (PMID 31353815, 2019). "The author reasoned that the targeting of LPP by a siRNA (siLLP) could reduce tumor vessel amount and leakiness, thus increasing PTX permanence in the tumor site." (PMID 31652539, 2019). "Blood samples collected from animals with LPP-shRNA expressing NIC tumours did not produce any CTC-derived colonies while NIC-tumour bearing mice from the control cohort (Luc-shRNA) produced an average of 123.6±7.8 colonies." (PMID 28436416, 2017). "The analysis highlighted that for the LPP gene, a varying degree of methylation depending on the position in the gene can be observed; however, there is no statistical difference between tumor and normal tissue in LUAD at the promoter region." (PMID 41441397, 2025). "As in the case of LPP, the TENM4 gene also displays a varying degree of methylation depending on the region, and tumor vs. normal tissue, with no statistical significance of the methylation sites in the promoter region for normal vs. tumor tissue in both LUAD and LUSC." (PMID 41441397, 2025).
cancer (22 papers, 2010 to 2025). A tumor composed of atypical neoplastic, often pleomorphic cells that invade other tissues. "As hypomethylation is a hallmark of cancer cells and this further correlates with increased transposons activity, we investigated the methylation status of the LPP and TENM4 genes that harbor L2-derived miR-28-5p and miR-708-5p, respectively." (PMID 41441397, 2025). "The highest burden of 3′ UTR mutations are found in FLRT2 and LPP (mutated in 20 and 15 patients, respectively), which are both cell adhesion proteins associated with cancer." (PMID 37516102, 2023). "In fact, LPP was shown to act as a suppressor of cell migration associated with malignant cancer phenotypes." (PMID 34867475, 2021). "For example, in TPRG1 associated with HNSCC potential oncogene TP63, LPP played the role of cancer cell migration, and CCDC50 was essential for cancer cell survival." (PMID 32455963, 2020). "As a promoter of mesenchymal/fibroblast migration, LPP is involved in cancer cell migration and invasion in a variety of cancers." (PMID 33371071, 2020). "Their host genes had been described in individual studies with regard to their roles in either PCa progression (e.g., CRIM1, NEAT1, and STIL) or other cancers (e.g., LPP and RHOBTB3)." (PMID 33105568, 2020). "Two top-ranked genes identified by the method, CD44 (1st) and LPP (2nd), are known to promote cancer cell dissemination and metastasis growth after genomic alteration." (PMID 30459309, 2018). "In contrast to its promigratory effect in LPP-overexpressing cultured cells or cancer cell lines, LPP may act as a fine-tuning protein regulating the migratory behavior of vascular SMC in response to biomechanical stimulation." (PMID 34867475, 2021). "LPP may partner with different molecules and reflect its various functions, therefore, LPP may exert as potential oncogene or oncosuppressor gene in different cancer cell lines 45,46." (PMID 31523167, 2019). "Although LASP-1 sequence analysis revealed no nuclear localisation signal, the classical import pathway for the nucleus, LASP-1 binds to the well-characterised shuttle proteins and transcription factors LPP and Zyxin that are upregulated in a wide variety of human cancers." (PMID 20461080, 2010). "As previously shown, reducing LPP levels or impairing LPP interactions with the actin cytoskeleton impaired gelatin degradation; thus, we sought to determine whether this loss of ECM degradation was due to an inability of cancer cells to upregulate or secrete MMPs." (PMID 28436416, 2017).
benign tumors (1 paper, 2005). "In the course of our studies of chromosomal aberrations in benign tumors, we have previously discovered the LPP gene as being rearranged in certain subtypes of these tumors, and identified the LPP protein as a member of the zyxin family of proteins." (PMID 15649318, 2005). "Originally, we identified the LPP gene, as being the preferred translocation partner of the HMGA2 gene in a subgroup of lipomas, which are benign tumors of adipose tissue." (PMID 15649318, 2005).
LPP also shares sentences with these, for which no sentence is quoted: Colon Cancer (2 papers); colorectal cancer (2); infection (2); juvenile idiopathic arthritis (2); leukemia (2); multiple myeloma (2); prostate carcinoma (2); vitiligo (2); Addison’s diseases (1); asthma (1); atopic dermatitis (1); bladder cancer (1); breast (1); cardiac hypertrophy (1); cardiomyopathy (1); chondroma (1); diabetes (1); dilated cardiomyopathy (1); dyslipidemia (1); fibrosarcoma (1); heart disease (1); melanoma (1); myxoid liposarcoma (1); neurological disease (1); non-small cell lung carcinoma (1); ovarian tumor (1); pancreatic cancer (1); papillary thyroid carcinomas (1); pollen allergies (1); primary biliary cirrhosis (1).
A further 11 diseases each share a sentence with LPP in 1 paper.